MEF2C (myocyte enhancer factor 2C)
Diseases named in the same sentence as MEF2C in open-access papers (continued):
Sharing a sentence is not in itself a finding about the gene and the disease.
Parkinson disease (5 papers, 2008 to 2024). A progressive degenerative disorder of the central nervous system characterized by loss of dopamine producing neurons in the substantia nigra and the presence of Lewy bodies in the substantia nigra and locus coeruleus. "Some pro-apoptotic genes were downregulated after hypoxic preconditioning like Mef2c, a transcription factor involved in neuronal loss in Parkinson's disease and in the regulation of apoptosis in macrophages." (PMID 18261226, 2008). "Mef2c triggers apoptosis in macrophages and may be involved in dopaminergic neuron death in Parkinson's disease." (PMID 18261226, 2008). "Interestingly, using a human iPS cells-derived model of Parkinson’s disease, it was found that the myocyte enhancer factor 2C-peroxisome proliferator-activated receptor-γ coactivator-1α (MEF2C-PGC1α) pathway may be a new therapeutic target for Parkinson’s disease." (PMID 32751747, 2020).
Angelman syndrome (4 papers, 2013 to 2023). A neurogenetic disorder characterized by severe intellectual deficit and distinct facial dysmorphic features.
brain ischemia (4 papers, 2019 to 2025). Diminished or absent blood supply to the brain caused by obstruction (thrombosis or embolism) of an artery resulting in neurologic damage. "MEF2C overexpression mitigates apoptosis in cerebral ischemia preconditioning and suppresses inflammation and oxidative stress by inhibiting NF-κB phosphorylation." (PMID 40362577, 2025). "It is known that p38s and ERK5 can trigger phosphorylation of MEF2c and then increase c-Jun expression, which is distinct among several diseases like brain ischemia, injury, cell death, neuro-inflammatory, and neurodegenerative disease." (PMID 33727915, 2021). "Constitutively expressing MEF-2C in both in vivo and in vitro systems yielded pure neurons and MEF-2C-directed neuronal progenitor cells can successfully differentiate into functional neurons in mouse models of cerebral ischemia and can improve behavioral defects." (PMID 31105874, 2019). "These proteins include BPTF and MEF2C, which govern microglial homeostatic responses; MEF2A, which promotes autophagy; and ZEB1, which mediates protective effects after brain ischemia (Set 2)." (PMID 38178204, 2024).
cognitive decline (4 papers, 2018 to 2024). "However, in the same study aggregate associations of SNPs within the MEF2C and HLA loci were associated with cognitive decline." (PMID 30620773, 2018). "In addition, the involvement of cGAS-STING in tau-related cognitive decline has been identified, resulting in the inhibition of neuronal expression of myocyte-specific enhancer factor 2C(MEF2C) expression." (PMID 38467840, 2024).
colorectal cancer (4 papers, 2011 to 2023). A primary or metastatic malignant neoplasm that affects the colon or rectum. "Data showing its upregulation in colorectal cancer during disease progression and its association with BC invasion support a MEF2C pro-oncogenic function." (PMID 33673112, 2021).
embryonic carcinoma (4 papers, 2017 to 2023). "We examined the role of ARP5 in MYOCD–SRF and MEF2C function using the murine p19 embryonic carcinoma P19CL6 cell line." (PMID 36610028, 2023).
Hyperglycemia (4 papers, 2018 to 2025). An increased concentration of glucose in the blood. "Evidence shows miRNA-373 to have protective effects against hyperglycemia-induced cardiac downregulating of the myocyte enhancer factor 2C (MEF2C) gene, which codes for the hypertrophic protein." (PMID 39859467, 2025). "Based on this model, we speculate that Mef2c induction by FGF1 contributes to a sustained reduction in the excitability of hypothalamic neurocircuits that raise the BG level when activated, leading to synaptic DCV accumulation and potentially contributing to sustained amelioration of hyperglycemia." (PMID 32895383, 2020).
left ventricular hypertrophy (4 papers, 2009 to 2023). Enlargement of the LEFT VENTRICLE of the heart. "In addition, MEF2C deficiency alleviated the left ventricular hypertrophy induced by pressure overload through regulating the mTOR/S6K pathway in mice." (PMID 33817315, 2021). "Mef2c silencing alleviates pressure-induced left ventricular hypertrophy by modulating the mTOR/S6K pathway." (PMID 37221368, 2023). "MEF2C silencing attenuated load-induced left ventricular hypertrophy by modulating mTOR/S6K pathway in mice." (PMID 34054926, 2021). "A key finding in the current study is the attenuation of the load-induced left ventricular hypertrophy induced by MEF2C silencing." (PMID 20041152, 2009). "In this study, we investigated whether MEF2C plays a role in mediating the left ventricular hypertrophy by pressure overload in mice." (PMID 20041152, 2009). "Next we investigated whether MEF2C silencing affects the load-induced left ventricular hypertrophy." (PMID 20041152, 2009).
liver cancer (4 papers, 2015 to 2024). An epithelial or non-epithelial malignant neoplasm that arises from the liver. "MEF2C diversifies hematological tumors, pancreatic cancer or liver cancer, leading to exhibition of various tumor characteristics." (PMID 34991657, 2022). "The dual role of MEF2C in tumors has also been reported in liver cancer." (PMID 34991657, 2022). "Seven TFs (FOXA1, FOXA2, RARG, STAT4, MEF2C, SOX18, and GXS2) have been identified to be likely to affect the metabolism, development, differentiation and proliferation of liver cancer in previous studies." (PMID 29033978, 2017).
mental disorder (4 papers, 2020 to 2023). A disease that has its basis in the disruption of mental process. "Further research on MEF2C will elucidate on the pathogenesis of neurological and mental disorders, as well as provide insights for improvement of symptoms associated with MEF2C gene deficiencies in neuropsychiatric disorders." (PMID 34991657, 2022). "LINC00461 affects the expression levels of its neighbor gene MEF2C, which plays a vital role in neurodevelopment relevant to mental disorders." (PMID 35081922, 2022).
pancreatic cancer (4 papers, 2014 to 2024). "Hesperetin inhibited p38 phosphorylation and MEF2C expression, similar to its effects in other studies on pancreatic cancer and neuritis." (PMID 39339707, 2024). "YY1 acts as tumor suppressor, suppresses invasion and metastasis of pancreatic cancer cells by downregulating MMP10 which is upregulated by Mef2c." (PMID 38110859, 2023). "YY1 suppresses invasion and metastasis of pancreatic cancer cells by downregulating MMP10 in a MUC4/ErbB2/p38/MEF2C-dependent mechanism." (PMID 24884523, 2014). "We also explored the potential mechanisms underlying the tumor suppression role of YY1 and found that YY1 suppresses invasion and metastasis of pancreatic cancer cells by downregulating MMP10 in a MUC4/ErbB2/p38/MEF2C-dependent mechanism." (PMID 24884523, 2014). "The YY1 high-level overexpression suppresses invasion and metastasis of pancreatic cancer cells by downregulating MMP10 via a MUC4/ErbB2/p38/MEF2C-dependent mechanism." (PMID 24884523, 2014). "Another important role of Mef2c is also seen in pancreatic cancer." (PMID 38110859, 2023). "A report indicated that YY1 could suppress invasion and metastasis by downregulating MMP10 in a MUC4/ErbB2/p38/MEF2C-dependent manner in pancreatic cancer cells, suggesting MEF2C phosphorylation is required for MMP10 expression." (PMID 30836712, 2019).
pancreatic ductal adenocarcinoma (4 papers, 2014 to 2023). An infiltrating adenocarcinoma that arises from the epithelial cells of the pancreas. "As described in other studies, the up regulation of Mef2c promotes invasion and metastasis of pancreatic ductal adenocarcinoma." (PMID 29383134, 2017). "As far as ME2C is concerned, it demonstrated its activation by the MAPK p38 in inflammation in monocytic cells, whereas downregulation of the MUC4/ErbB2/p38/MEF2C‐dependent pathway was shown to suppress invasion and metastasis of pancreatic ductal adenocarcinoma." (PMID 31930767, 2020). "Therefore, we presume that YY1 suppresses invasion and metastasis of pancreatic ductal adenocarcinoma by downregulating MMP10 in a MUC4/ErbB2/MEF2C-dependent mechanism." (PMID 24884523, 2014).
rhabdomyosarcoma (4 papers, 2013 to 2022). A rare aggressive malignant mesenchymal neoplasm arising from skeletal muscle. "In total, our experiments show that the NOTCH1/SNAI1 axis suppresses MEF2C expression, locking cells in a less differentiated cell state while elevating the overall self-renewal potential of rhabdomyosarcoma." (PMID 28614716, 2017). "A previous study which assayed gene expression changes in a murine model of alveolar rhabdomyosarcoma detected a down regulation of Mef2c in these tumors." (PMID 24279793, 2013). "Rather, once differentiation programs are initiated by MEF2C, self-renewal programs are actively turned off, suggesting important insights into how self-renewal and differentiation programs are reciprocally regulated in muscle and rhabdomyosarcoma growth." (PMID 28614716, 2017). "In rhabdomyosarcoma cells compared to normal myoblasts, MEF2D expression tended to be lost and a less active isoform of MEF2C tended to be expressed." (PMID 26506234, 2016). "MEF2C and MEF2D may also act as tumor suppressors in rhabdomyosarcoma." (PMID 26506234, 2016).
salivary gland tumor (4 papers, 2024 to 2025). "Microsecretory adenocarcinoma (MSA) is a newly identified entity in the WHO classification of salivary gland tumors characterized by MEF2C::SS18 fusion." (PMID 40176070, 2025). "Microsecretory adenocarcinoma was identified as a newly discovered salivary gland tumor via molecular studies that showed a low-grade adenocarcinoma with a specific MEF2C:SS18 fusion." (PMID 38929710, 2024). "Currently, MEF2C::SS18 fusion has been reported in microsecretory adenocarcinoma (MSA), a novel subtype of salivary gland adenocarcinoma that tends to be less malignant or appears as an inert salivary gland tumor." (PMID 38907739, 2024).
T-cell acute lymphoblastic leukemia (4 papers, 2013 to 2023). Acute lymphoblastic leukemia of T-cell origin. "Aberrant activation has been reported in acute T-cell leukemia, whereby MEF2C is directly regulated by an oncogenic homeodomain TF, NKX2–5, or targeted by genomic deletions of non-coding regulatory regions." (PMID 26473286, 2015).
tauopathy (4 papers, 2022 to 2024). Neurodegenerative disorders involving deposition of abnormal tau protein isoforms (tau proteins) in neurons and glial cells in the brain. "Loss of MEF2C is associated with heightened IFN-I signature in microglia during aging and β-amyloidosis, while IFN-I signaling in neurons diminishes MEF2C-associated cognitive resilience in tauopathy." (PMID 38774266, 2024). "The MEF2C target genes changed by DMXAA overlapped with those altered by Cgas deletion in tauopathy mice." (PMID 37095396, 2023). "We further characterized a brain-permeable cGAS inhibitor and showed that pharmacological inhibition of cGAS protected against cognitive impairment in P301S tauopathy mice and enhanced neuronal MEF2C transcriptional network." (PMID 37941028, 2023). "Our analysis revealed that microglial IFN-I negatively impacted neuronal expression of MEF2C and its target genes in tauopathy." (PMID 37941028, 2023).
cervical cancer (3 papers, 2021 to 2023). A primary or metastatic malignant neoplasm involving the cervix. "On the other hand, in cervical cancer, several tumorigenic processes, like proliferation, migration, and invasion, were inhibited when MEF2C’s expression levels were upregulated." (PMID 37762600, 2023). "Early work reported that ERK5 mediates serum- and EGF-induced proliferation of cervical cancer HeLa cells, by phosphorylating and promoting transcriptional activation of MEF2C and transcription of c-Jun." (PMID 36123565, 2022). "Meanwhile, according to MCC scores from the CytoHubba plugin in Cytoscape, the top 5 cervical cancer-related genes were screened out (MEF2C, CXCL16, IRF4, OAS3, PTGER3)." (PMID 34020619, 2021).
cyst (3 papers, 2012 to 2023). A sac-like closed membranous structure that may be empty or contain fluid or amorphous material. "In Pkd2-deficient mice, the reduction of HDAC5 inhibits cyst formation by enhancing MEF2C-dependent transcription." (PMID 37878054, 2023). "Determining when this is the appropriate action is an area of future research.HDAC5 upregulates MEF2C; in turn, MEF2C is known to be missing during metastasis, the latter of which is necessary for ciliogenesis; conversely, inhibition of HDAC5 suppresses cyst formation that disrupts cilia formation." (PMID 35859153, 2022).
DiGeorge syndrome (3 papers, 2017 to 2020). "In this study, we showed that inactivation of Tbx1 in the AHF using Mef2c-AHF-Cre allele, results in a PTA that is also observed in the most seriously affected 22q11.2DS (velo-cardio-facial/DiGeorge syndrome) patients." (PMID 28346476, 2017).
Insulin resistance (3 papers, 2013 to 2025). Increased resistance towards insulin, that is, diminished effectiveness of insulin in reducing blood glucose levels. "Recently, MEF2C has also been implicated in the pathogenesis of insulin resistance, an important risk factor for vascular disease." (PMID 23776548, 2013). "Birds with low MEF2C expression showed an insulin resistance with significantly higher blood glucose levels after 3 h of fasting and had similar insulin concentration." (PMID 33370292, 2020). "Reduces inflammation, improves gut microflora, alleviates insulin resistance (PI3K/AKT/GLUT4, FOXO1), reduces inflammatory markers, promotes muscle growth (MyHC, Sirt1, PGC-1α, MEF2C, AMPK)." (PMID 41404330, 2025).
lung carcinoma (3 papers, 2016 to 2024). "Second, we studied the effects of Mef2c deletion on anti-tumor immunity, by using syngeneic models of lung cancer (TC1 tumor cells injected subcutaneously)." (PMID 34290714, 2021). "We now report that as with Mef2d, the deletion of Mef2c in Tregs switches off the expression of Il10 and Icos and leads to enhanced antitumor immunity in syngeneic models of lung cancer." (PMID 34290714, 2021).
myeloma (3 papers, 2021 to 2023). "In the case of MEF2C, the set of its predicted target TF, includes archetypical myeloma PC dependencies, i.e., IRF4, PRDM1, thus in part explaining the high degree of myeloma cell dependency on MEF2C." (PMID 34521827, 2021). "Recently, ATAC-seq profiling suggested MEF2 family is preferentially enriched in the open chromatin regions in myeloma cells and MEF2C inhibition resulted in reduced myeloma cell growth and survival." (PMID 33963182, 2021). "A high level of myeloma cell line dependency to MEF2C in the DepMap CRISPR/Cas9 screen, highlights an important role of this TF in the biology of MM, least because of its inferred role in activating transcription of TF such as IRF4, XBP1 and PRDM1." (PMID 34521827, 2021). "In multiple myeloma (MM), four Supertarget genes encode transcription factors such as interferon regulatory factor 4 (IRF4), PR/SET domain 1 (PRDM1), POU class 2 homeobox associating factor 1 (POU2AF1), and myocyte enhancer factor 2C (MEF2C)." (PMID 37297004, 2023).
myocardial infarction (3 papers, 2013 to 2024). Gross necrosis of the myocardium, as a result of interruption of the blood supply to the area, as in coronary thrombosis. "Two recent reports demonstrated that following myocardial infarction delivery of Gata4, Mef2c, and Tbx5, or GATA4, HAND2, MEF2C, and TBX5 in the injured myocardium successfully reprogrammed cardiac fibroblasts into cardiomyocytes." (PMID 23704920, 2013).
nemaline myopathy (3 papers, 2022 to 2023). Nemaline myopathy (NM) encompasses a large spectrum of myopathies characterized by hypotonia, weakness and depressed or absent deep tendon reflexes, with pathologic evidence of nemaline bodies (rods) on muscle biopsy. "MEF2C levels were significantly increased in muscles of patients with AD nemaline myopathy (the mean log2-fold change was 0.90 adjusted P = 0.006)." (PMID 36196089, 2022). "We did not observe increased Mef2c expression in mouse models for Duchenne muscular dystrophy and nemaline myopathy." (PMID 37395273, 2023).
osteoarthritis (3 papers, 2014 to 2022). A noninflammatory degenerative joint disease occurring chiefly in older persons, characterized by degeneration of the articular cartilage, hypertrophy of bone at the margins and changes in the synovial membrane. "HBM has been associated with both ligament ossification and increased prevalence of joint replacement (potentially due to osteoarthritis) and, more recently, genetic markers for MEF2C and SOX6, which both have regulatory roles in endochondral ossification." (PMID 24606091, 2014).
prostate carcinoma (3 papers, 2010 to 2022). A carcinoma that arises from epithelial cells of the prostate gland. "In addition, reduction of cyclin D1 and myocyte-specific enhancer factor 2C (MEF2C) transcriptional activity in prostate cancer cells was noted." (PMID 31106201, 2019). "The down-regulation of LAMB2 and MEF2C might be involved with cell adhesion or motility in invasive prostate cancer cells and apoptosis via BCL2 transformation, respectively." (PMID 20969748, 2010).
pulmonary arterial hypertension (3 papers, 2016 to 2019). Pulmonary arterial hypertension (PAH) is a group of diseases characterized by mean pulmonary artery pressure >20 mmHg and elevated pulmonary arterial resistance leading to right heart failure. "Using Ingenuity Pathway Analysis (IPA), we discovered a strong association among pulmonary hypertension, MEF2C, LMOD1, and miR-214." (PMID 27144530, 2016). "There is evidence for miRNA regulation of MEF-2C; miR-214 suppresses the activity of MEF-2C:MYOCD:Leiomodin1(LMOD-1) signaling pathway, and excessive proliferation of smooth muscle cells causing pulmonary arterial hypertension." (PMID 31105874, 2019).
sarcopenia (3 papers, 2019 to 2024). Progressive decline in muscle mass due to aging which results in decreased functional capacity of muscles. "In the future, the regulation of AChR-β by the IL-6/IL-6R-ERK1/2-PGC1α/MEF2C pathway should be investigated in patients and animals with sarcopenia." (PMID 39390392, 2024). "Thus, the activation of MEF2c during aging may contribute to cellular remodeling in sarcopenia." (PMID 33375170, 2020).
Viral infection (3 papers, 2016 to 2025). "Finally, the cell viability assay verified a reduction in ATP level by 15% and 17% at 48 and 72 h after Mef2c-KD virus infection in NSC-34 cells, respectively, suggesting elevation of cells energy demand." (PMID 39920775, 2025).
acute leukemia (2 papers, 2019 to 2022). A clonal (malignant) hematopoietic disorder with an acute onset, affecting the bone marrow and the peripheral blood. "MEF2C was significantly up-regulated in acute leukemia with MLL-R, while known as an adverse prognostic marker in AML." (PMID 31523525, 2019). "MEF2C-eGFP mice, therefore, recapitulate patients with ETP-ALL with multilineage marker expression similar to human mixed phenotype acute leukemia (MPAL)." (PMID 35536646, 2022). "Enforced MEF2C expression in mouse or human progenitor cells effectively blocks early T cell differentiation and promotes the development of biphenotypic lymphoid tumors that coexpress CD3 and CD19, resembling human mixed phenotype acute leukemia." (PMID 35536646, 2022).